RBM20 (RNA binding motif protein 20)
Description:
RNA-binding protein that acts as a regulator of mRNA splicing of a subset of genes encoding key structural proteins involved in cardiac development, such as TTN (Titin), CACNA1C, CAMK2D or PDLIM5/ENH. Acts as a repressor of mRNA splicing: specifically binds the 5'UCUU-3' motif that is predominantly found within intronic sequences of pre-mRNAs, leading to the exclusion of specific exons in target transcripts. RBM20-mediated exon skipping is hormone-dependent and is essential for TTN isoform transition in both cardiac and skeletal muscles. RBM20-mediated exon skipping of TTN provides substrates for the formation of circular RNA (circRNAs) from the TTN transcripts. Together with RBM24, promotes the expression of short isoforms of PDLIM5/ENH in cardiomyocytes (By similarity).
Tractability: PROTAC: ubiquitination databases record sites on it.
Gene: Protein-coding gene on chromosome 10 (110,643,948 to 110,839,471, forward strand). Ensembl gene ENSG00000203867.
Subcellular location: Nucleus; Cytoplasm, Cytoplasmic ribonucleoprotein granule
Subcellular location (Human Protein Atlas): Golgi apparatus; Nucleoplasm; Cytokinetic bridge; Nucleoli
Gene Ontology:
Molecular function: pre-mRNA intronic binding; protein binding; splicing factor binding; RNA binding; nucleic acid binding; zinc ion binding
Biological process: heart formation; negative regulation of mRNA splicing, via spliceosome; positive regulation of RNA splicing; regulation of mRNA splicing, via spliceosome; spliceosome-depend formation of circular RNA; regulation of alternative mRNA splicing, via spliceosome; regulation of RNA splicing
Cellular component: cytoplasmic ribonucleoprotein granule; nucleus
Genetic constraint (gnomAD): Loss-of-function variants: 42 observed, 95.7 expected, observed/expected ratio (o/e) 0.44, 90% interval 0.34 to 0.57. The upper end of that interval is the gene's LOEUF score, 0.57, which puts it in group 2 of 6, group 1 being the genes least tolerant of losing a copy. Missense variants: 1,416 observed, 1,493.9 expected, observed/expected ratio (o/e) 0.95, 90% interval 0.91 to 0.99. Synonymous variants: 557 observed, 589.63 expected, observed/expected ratio (o/e) 0.94, 90% interval 0.88 to 1.01.
Gene-disease validity (ClinGen):
ClinGen rates the evidence that RBM20 causes each of these diseases.
dilated cardiomyopathy (autosomal dominant): Definitive. Cardiomyopathy which is characterized by dilation and contractile dysfunction of the left and right ventricles.
hypertrophic cardiomyopathy (autosomal dominant): Limited. A condition in which the myocardium is hypertrophied without an obvious cause.
Homologues: Orthologues: chimpanzee RBM20 (97% identical), macaque RBM20 (95% identical), dog RBM20 (86% identical), rabbit RBM20 (84% identical), rat Rbm20 (78% identical), mouse Rbm20 (77% identical), pig RBM20 (69% identical), guinea pig RBM20 (52% identical), tropical clawed frog rbm20 (44% identical), Caenorhabditis elegans hrpl-1 (6% identical), Drosophila melanogaster sm (6% identical). Paralogues in human: PTBP1 (11% identical), HNRNPL (11% identical), PTBP2 (9% identical), PTBP3 (9% identical), HNRNPLL (9% identical).
Diseases named in the same sentence as RBM20 in open-access papers:
RBM20 is named in the same sentence as 73 diseases in open-access papers, as found by Europe PMC text mining. Sharing a sentence is not in itself a finding about the gene and the disease. The quoted sentences say what the papers report.
dilated cardiomyopathy (59 papers, 2013 to 2026). "Surprisingly, we found RNA-binding motif protein 20 (RBM20), an alternative splicing regulator associated with dilated cardiomyopathy, to be expressed in cortical parvalbumin interneurons and mitral cells of the olfactory bulb." (PMID 41524378, 2026). "Variants in RBM20 are associated with dilated cardiomyopathy that presents with an increased risk of arrhythmias and heart failure at a young age." (PMID 41561974, 2025). "Individuals diagnosed with dilated cardiomyopathy (DCM) who possess RBM20 mutations frequently have compromised cardiac function and are prone to experiencing atrial fibrillation, ventricular arrhythmia, and sudden cardiac death." (PMID 39200108, 2024). "Human patients carrying genetic mutations in RNA binding motif 20 (RBM20) develop a clinically aggressive dilated cardiomyopathy (DCM)." (PMID 37219949, 2023). "The authors show that loss-of-interaction with the nuclear importer, TNPO3, causes cytoplasmic mislocalization of RBM20 variants linked to severe cases of dilated cardiomyopathy." (PMID 37463913, 2023). "Here, we apply this combinatorial approach for the first time to decipher the mechanism of dilated cardiomyopathy (DCM) caused by mislocalized RBM20." (PMID 37463913, 2023). "We employ a combination of the viral vector AAVMYO with superior targeting specificity of heart muscle tissue and CRISPR base editors to repair patient mutations in the cardiac splice factor Rbm20, which cause aggressive dilated cardiomyopathy." (PMID 37349314, 2023). "Severe forms of dilated cardiomyopathy (DCM) are associated with point mutations in the alternative splicing regulator RBM20 that are frequently located in the arginine/serine-rich domain (RS-domain)." (PMID 37463913, 2023). "Missense mutations in the arginine/serine (RS) domain of RBM20 lead to abnormal gene splicing and have been linked to severe dilated cardiomyopathy (DCM) in human patients and animal models." (PMID 36140694, 2022). "Pathogenic variants in RBM20 have been identified in patients with autosomal dominant (AD) dilated cardiomyopathy." (PMID 35911904, 2022). "In this review, we focus on RBM20, a gene that is associated with highly aggressive arrhythmogenic phenotypes in patients diagnosed with dilated cardiomyopathy (DCM) in spite of an apparently normal heart or scattered heart alterations." (PMID 33671899, 2021). "Previous reports indicated that mutations in Rbm20 clinically cause severe form of dilated cardiomyopathy (DCM)." (PMID 34523260, 2021). "Originally, RBM20 mutations were discovered to cause the development of dilated cardiomyopathy by erroneous splicing of the gene TTN (titin)." (PMID 33450993, 2021). "By analyzing the isoforms in the presence of RNA Binding Motif Protein 20 (RBM20) mutations associated with aggressive dilated cardiomyopathy (DCM), we identify 121 differentially expressed transcript isoforms in 107 cardiac genes." (PMID 34244519, 2021). "Recently, alterations in RBM20 have been associated with a severe arrhythmogenic phenotype in dilated cardiomyopathy (AR-DCM), leading to high risk for SCD." (PMID 33671899, 2021). "This review aims to give an update on recent findings related to the cardiac splicing factor RNA-binding motif protein 20 (RBM20) and RBM20 cardiomyopathy, a form of dilated cardiomyopathy caused by mutations in RBM20." (PMID 32789749, 2020). "RNA-binding motif protein 20 (RBM20) is a splicing factor implicated in dilated cardiomyopathy (DCM), which regulates the alternative splicing within the I-band of the titin gene." (PMID 30898135, 2019). "Genetic variants of RBM20 are associated with dilated cardiomyopathy such as heart failure with preserved ejection fraction both in humans and in animal models." (PMID 31092860, 2019).
dilated cardiomyopathy (continued). "In mice, mutations in Rbm20 result in dilated cardiomyopathy (DCM) with similar severity to Ttn mutations, and arrhythmia that is more severe than Ttn mutations, indicating a role for other Rbm20 targets in disease." (PMID 31888141, 2019). "The RNA binding protein RBM20, linked to human dilated cardiomyopathy, was found to mediate splicing of some titin exons; mutations in RBM20 resulted in persistence of the large embryonic isoform N2BA-G into adulthood." (PMID 27914791, 2017). "Mutations in the RNA-binding protein (RBP) and splicing factor RNA-binding motif protein 20 (RBM20) cause an aggressive form of dilated cardiomyopathy (DCM)." (PMID 28850611, 2017). "As such, mutations in the splice factor RBM20 have recently been associated with human dilated cardiomyopathy." (PMID 26116573, 2015). "The relationship of RBM20 mutations to human dilated cardiomyopathy was first reported by Brauch and coworkers." (PMID 24367651, 2013). "Mutations in the RBM20 gene are linked to an aggressive form of dilated cardiomyopathy." (PMID 41524378, 2026). "A carefully performed experimental analysis of the R636S variant of human RNA-binding motif protein-20 (RBM20) that has been causally linked to development of dilated cardiomyopathy, revealed dysregulation of RNA-protein condensates in the cytosol as the pathogenic mechanism." (PMID 39932799, 2025). "Unsurprisingly, mutations in RBM20 have been associated with dilated cardiomyopathies in humans." (PMID 38818408, 2024). "Variants in RBM20 are reported in 2% to 6% of familial cases of dilated cardiomyopathy and may be associated with fatal ventricular arrhythmia and rapid heart failure progression." (PMID 37593875, 2023). "RBM20 is a disease-causing gene associated with dilated cardiomyopathy (DCM)." (PMID 35181673, 2022). "RBM20 is one of the genes predisposing to dilated cardiomyopathy (DCM)." (PMID 36198914, 2022). "Amongst the 27 potentially new TE-RBPs was the muscle-specific and dilated cardiomyopathy-associated splicing regulator RBM20, whose expression correlated particularly well with the TE of 163 experimentally validated target genes (out of 561 total targets; Glass’ Δ = 7.0)." (PMID 34879078, 2021). "RBM20 has initially been identified as one of dilated cardiomyopathy (DCM)-linked genes." (PMID 30547036, 2018). "Loss of RNA-binding motif protein 20 (RBM20) may cause dilated cardiomyopathy most probably because it is necessary for normal splicing of many cardiac genes." (PMID 30368217, 2018). "In addition to titin, RBM20 controls the splicing fates of crucial cardiac genes such as CamkIIδ, and RyR2, such that RBM20 gene mutation causes mis-splicing events of these cardiac genes, resulting in early onset dilated cardiomyopathy." (PMID 38818408, 2024). "Hence, the use of drugs to increase RBM20 expression might be a potentially effective treatment approach for individuals with dilated cardiomyopathy who have RBM20 mutations on one of their gene copies (heterozygous)." (PMID 39200108, 2024). "Here, we review our current knowledge of muscle-specific splicing factors and heart disease, with an emphasis on RBM20 and its targets, RBM20-dependent alternative splicing mechanism, RBM20 disease origin in induced Pluripotent Stem Cells (iPSCs), and RBM20 mutations in dilated cardiomyopathy." (PMID 29304022, 2018). "The recent discovery of the muscle-specific splicing factor RNA-binding motif 20 (RBM20) not only provided great insights into the general alternative splicing mechanism but also demonstrated molecular mechanism of how this splicing factor is associated with dilated cardiomyopathy." (PMID 29304022, 2018). "RBM20 mutations may account for as many as 3% of dilated cardiomyopathy patients." (PMID 24367651, 2013). "RBM20 is extensively studied and regarded as a regulator in the process of sarcoplasmic reticulum Ca2+ release in severe arrhythmogenic dilated cardiomyopathy." (PMID 40288647, 2025).
dilated cardiomyopathy (continued). "Rare diseases (monogenic), such as hypertrophic cardiomyopathy (e.g., MYBPC3, MYH7 mutations), dilated cardiomyopathy (LMNA, RBM20), or inherited arrhythmias (KCNQ1, RYR2), are often caused by single, well-characterized mutations." (PMID 40465697, 2025). "For instance, Rbm20 knockout mice exhibit dilated cardiomyopathy (DCM) due to the disrupted splicing of genes such as Titin and Camk2d, impairing sarcomere structure and calcium signaling." (PMID 40076920, 2025). "Other notable targets include PLN (phospholamban), involved in calcium handling abnormalities in dilated cardiomyopathy (DCM), and RBM20, a gene associated with RNA splicing defects in heart failure." (PMID 40465697, 2025). "In particular, mutations of RBM20 and RBFOX2 are associated with dilated cardiomyopathy, hypertrophic cardiomyopathy, or hypoplastic left heart syndrome." (PMID 38535111, 2024). "Research has demonstrated that ATRA has the ability to enhance RBM20 expression and partially re-verse the in vitro dilated cardiomyopathy (DCM) characteristics." (PMID 39200108, 2024). "This is the RNA-binding motif protein 20 (RBM20), a well-studied heart and muscle-specific splicing factor mutations in which can cause inherited dilated cardiomyopathy." (PMID 37272356, 2023). "Genetic ablation of Rbm20 results in aberrant gene splicing and dilated cardiomyopathy (DCM) in rodents." (PMID 36140694, 2022). "RNA binding motif 20 (RBM20) cardiomyopathy has been detected in approximately 3% of populations afflicted with dilated cardiomyopathy (DCM)." (PMID 34523260, 2021). "The inhibition of RBM20 (RNA‐binding motif protein 20) expression leads to dilated cardiomyopathy (DCM) in adults." (PMID 33295096, 2021). "Adaptive splice regulators, such as RNA-binding motif protein 20 (RBM20) determine the physiological mRNA landscape formation, and rare variants in the RBM20 gene explain up to 6% of genetic dilated cardiomyopathy (DCM) cases." (PMID 34575212, 2021). "Deficiency of Rbm20 in animal models leads to the development of dilated cardiomyopathy (DCM) and mutations in RBM20 have been identified in human patients with DCM." (PMID 29304022, 2018). "Despite that most circular RNAs are generated from constitutive exons in hearts, a critical splicing factor involved in dilated cardiomyopathy (i.e., RBM20) specifically regulates the generation of ecircRNAs from skipped exons corresponding to the I-band region of the Titin gene." (PMID 32429565, 2020). "In addition, both RBM20 and these Titin-derived circRNAs seem to regulate the progression of dilated cardiomyopathy, highlighting the importance of organ-specific biogenesis and function of circRNAs." (PMID 32429565, 2020). "For example, RBM20 is crucial for the formation of a subset of circRNAs that originate from the I-band of the titin gene, and these circRNAs are dynamically regulated in dilated cardiomyopathy." (PMID 30531834, 2019). "Moreover, AS of the titin gene has been linked to the regulatory activity of RNA binding motif protein 20 (RBM20), described as a regulator of cardiac AS and whose mutations have been associated with human dilated cardiomyopathy." (PMID 28374191, 2017). "Animals lacking RBM20 are predisposed to developing dilated cardiomyopathy and heart failure." (PMID 34523260, 2021). "Interestingly, RBM20 is among the most frequently affected genes in dilated cardiomyopathy." (PMID 32429565, 2020). "For example, dilated cardiomyopathy (DCM), which is defined by systolic dysfunction and dilation of one or both ventricles, can be caused in humans by mutations in the genes encoding cardiac phospholamban (PLN), delta-sarcoglycan (SGCD), and RNA-binding protein 20 (RBM20)." (PMID 31490923, 2019). "Therefore, RBM20 may be important for circRNA formation, which indicates new mechanistic insights for dilated cardiomyopathy." (PMID 30368217, 2018).
dilated cardiomyopathy (continued). "Strikingly, isoform ratios are tightly controlled during the perinatal period but are selectively altered in disease: in hypertrophic-, unlike in dilated cardiomyopathy, upregulation of RBM20 is driven largely by the alternative isoform." (PMID 42177204, 2026). "RBM20 and TTN are a pair of genes that are strongly related to dilated cardiomyopathy." (PMID 35207686, 2022). "Whereas mutations in ALPK3 have been associated with non-sarcomeric hypertrophic cardiomyopathy or dilated cardiomyopathy, BAG3 and RBM20 genes have been associated with dilated cardiomyopathy phenotype further highlighting a potential link between MVP and cardiomyopathy." (PMID 36873395, 2023).
cardiomyopathy (55 papers, 2013 to 2026). A disease of the heart muscle or myocardium proper. "The association of RBM20 mutations with cardiomyopathies has directed substantial research efforts to uncover its function in the heart and to understand the impact of cardiomyopathy-associated mutations." (PMID 41524378, 2026). "Another patient whose MYH7 variant was initially classified as VUS also had a rare nonsynonymous variant in RNA binding motif protein 20 (RBM20 p.Ile921Val), a titin-splicing gene implicated in cardiomyopathy." (PMID 40791945, 2025). "Loss or the dysregulated activity of several RBPs have been closely associated with cardiomyopathies in humans or in animal models, as exemplified by RBM20 mutations in DCM patients." (PMID 38535111, 2024). "A study showed that the association between variants on the TTN and RBM20 genes was responsible for a cardiomyopathy phenotype, and even more recently, the association of TTN and SRPK3 variants was associated with a skeletal myopathy phenotype." (PMID 39684706, 2024). "This variant is located within the arginine-serine-arginine-serine-proline stretch where missense mutations result in mislocalization of RBM20 to the cytoplasm and altered nuclear splicing of the pre-mRNAs of several cardiomyopathy-linked genes." (PMID 37593875, 2023). "Consecutive probands and relatives carrying RBM20 variants were retrospectively recruited from 12 cardiomyopathy units." (PMID 37593875, 2023). "Collectively, these results validate that the D1 sequence element is the core NLS in RBM20 and suggest that mutations in the D1 core NLS alone promote severe RBM20 cardiomyopathy via impaired nuclear import and accumulation in cytoplasmic granules." (PMID 37219949, 2023). "RNA binding motif 20 (RBM20) cardiomyopathy is a rare heart muscle disease caused by autosomal dominant mutations in the RBM20 gene." (PMID 37219949, 2023). "Mutations in the splicing factor RNA binding motif protein 20 (RBM20) cause severe forms of cardiomyopathy." (PMID 34273561, 2022). "RBM20 deficiency in rats leads to many phenotypic features that are observed in individuals with cardiomyopathy related to mutant RBM20, suggesting conserved RBM20 function." (PMID 35783855, 2022). "Because most RBM20 research has been in cardiac muscle as RBM20 mutations are linked to cardiomyopathies, understanding of its role in skeletal muscle remains limited." (PMID 36047761, 2022). "Mutations in genes encoding splicing factors often result in severe disease phenotypes in humans, as observed in cardiomyopathies which are often associated with mutations in RBM20." (PMID 34273561, 2022). "Since then, mutations in RBM20 were recognized as an important cause of cardiomyopathy and genotype-phenotype studies suggest many patients having a progressive and complicated clinical course." (PMID 34575212, 2021). "RBM20 is a cardiomyopathy-associated gene (MIM #613172), which is predominantly expressed in striated muscle with highest expression in the heart." (PMID 34201072, 2021). "RBM20 (RNA-binding motif protein 20) is a splicing factor targeting multiple cardiac genes, and its mutations cause cardiomyopathies." (PMID 33450993, 2021). "This review article highlights some of the recent advances in the field, ranging from aspects of granule formation to 3D genome architectures underlying RBM20-related cardiomyopathy." (PMID 34575212, 2021). "Mutations in the cardiac splicing factor RNA binding motif protein 20 (RBM20) are also known to be associated with severe cardiomyopathies." (PMID 34201072, 2021). "Cardiomyopathy-associated RBM20 variants cause overexpression of an RYR2-splice variant containing an additional small exon." (PMID 34575212, 2021). "Actually, a recent study identified two RBM20 regions (exons 9 and 11) with a significant risk for cardiomyopathy, ventricular and atrial arrhythmias, and even SCD." (PMID 33671899, 2021).